APC (APC regulator of Wnt signaling pathway)
Diseases named in the same sentence as APC in open-access papers (continued):
Sharing a sentence is not in itself a finding about the gene and the disease.
prostate carcinoma (continued). "In prostate cancer, the combination of BRCA2 and APC mutations was one of the most notable associations." (PMID 41395625, 2025). "Prostate cancers showed high rates of BRCA2 and APC co-mutations, indicating potential benefit from combined PARP and Wnt-targeted therapies." (PMID 41395625, 2025). "Our findings revealed that RSPO2 alterations occurred more frequently than those in other family members, as well as canonical Wnt regulators CTNNB1 and APC, providing insight into its potential significance in prostate cancer progression." (PMID 40711886, 2025). "A study by The Prostate Cancer Transatlantic Consortium (CaPTC) utilizing whole exome sequencing to determine genetic variants in Nigerian patients with advanced prostate cancer identified high frequencies of mutations in the BRCA1, BRCA2, APC, and ATM genes." (PMID 40313245, 2025). "A previous study measuring DNA methylation at GSTP1, APC, and RASSF1 loci in repeat prostate biopsies identified AA and EA men at risk of high-grade prostate cancer." (PMID 38566104, 2024). "Mouse models of prostate cancer can be generated by inducing stable forms of β-catenin or APC deletion." (PMID 38886806, 2024). "Although genetic alterations of APC, Axin1 and β-catenin have been detected in clinical specimens of advanced prostate cancer, the interaction between Axin1 and Wnt/β-catenin pathway in affecting prostate cancer progression is poorly understood." (PMID 38715121, 2024). "GSTP1, APC, and RASSF1 are three candidate tumor suppression genes, inactivated by hypermethylation, which have been implicated in higher-risk prostate cancers." (PMID 39202766, 2024). "The ConfirmMDx, which is based on the evaluation of the promoter methylation levels of three genes, namely GSTP1, APC and RASSF1 in prostate biopsy samples, was designed to identify men at lower risk for prostate cancer, thus avoiding repeated biopsies." (PMID 37511475, 2023). "For example, in early-stage prostate cancer, genes such as APC, RASSF1, GSTP1 undergo DNA hypermethylation." (PMID 37190171, 2023). "We identified ancestry-linked germline and somatic mutation frequencies in DNA damage repair genes (BRCA1, BRCA2, APC, and ATM), as well as three novel prostate cancer–associated genes (CACNA2D2, SYNE1, and ADAMTS2)." (PMID 36922933, 2022). "Our study showed for the first time that in a large population of NAW patients carrying the I1307K APC variant, there is an increased risk of overall cancer rate, in addition to an increased risk of CRC, melanoma, breast, and prostate cancer." (PMID 36497357, 2022). "We have shown that prostate carcinoma-associated epigenetic biomarkers including GSTP1, RASSF1﻿, RARb and APC are detectable in our cultures to confirm that these primary PDCOs indeed originated from tumor cells." (PMID 34581895, 2021). "MAK is overexpressed in prostate cancer cell lines and clinical specimens and leads to mitosis defects via APC/CCDH1 imbalance." (PMID 34722557, 2021). "PPAR-γ mediates cell cycle arrest and has tumor suppressor activity in liposarcoma, lung, and prostate cancers; and inhibits colonic polyp formation in adenomatous polyposis coli (APC) min/+ mice." (PMID 32498358, 2020). "In response to TGFβ stimulation, both Smad7 and p38 regulate the expression of adenomatous polyposis coli (APC), which is involved in microtubule organization and prostate cancer cell migration." (PMID 31771212, 2019).
prostate carcinoma (continued). "In human prostate cancer, PTEN loss is an early tumorigenic lesion, while Wnt-pathway activation through aberrations in APC, CTNNB1, RNF43, and RSPO2 are found in metastatic castration-resistant cancer, suggesting they are associated with tumor progression." (PMID 27536883, 2016). "Evidence from earlier studies has linked promoter hypermethylation of specific genes to pathogenesis and tumor progression in prostate cancer, e.g. APC, RARβ, and GSTP1." (PMID 24626295, 2014). "Several are known biomarkers for diagnosis and prognosis of prostate cancer (APC, GSTP1, KIT, PYCARD, PGDGRB, RARB, RARRES1, and TIMP1) and some though not biomarkers, were found to be dysregulated in the disease (CDKN1B, MMP7, and MMP9)." (PMID 24626295, 2014). "This is the first report to our knowledge that showed hypermethylation of RASSF1A and APC gene promoters in the prostate cancer samples derived from a Pakistani population." (PMID 23431474, 2013). "This is demonstrated with the APC gene found significantly differentially expressed in the prostate cancer study mentioned in the first use case." (PMID 22568834, 2012). "Several of the differentially expressed genes are known to play a critical role in prostate cancer, such as APC, MAPK7, or ZEB1." (PMID 22568834, 2012). "Patients with methylation in APC had higher prostate cancer mortality than patients with an unmethylated cancer." (PMID 22191037, 2011). "Hypermethylation of APC and RUNX3 was associated with increased risk of prostate cancer-specific mortality." (PMID 20671914, 2010). "For example, hypermethylation of p16 and APC is commonly observed in the early stages of prostate cancer." (PMID 20671914, 2010). "Moreover, APC deletion in combination with the prostate oncogene Hepsin overexpression facilitates prostate cancer progression." (PMID 38886806, 2024). "Thus, overexpression of β-catenin and APC is essential for the formation and advancement of prostate cancer since it promotes cell migration, survival, and proliferation, which in turn aids in tumour growth and metastasis." (PMID 39554609, 2024). "APC and CTNNB1 mutations are regularly found in prostate cancer." (PMID 34663878, 2021). "However, two or multiple genes cohort such as GSTP1/LGALS3 or GSTP1/RARβ2/APC has been shown to be more specific and sensitive biomarkers for prostate cancer." (PMID 25419445, 2012). "Promoter methylation in APC has been identified as a marker for prostate cancer prognosis." (PMID 22191037, 2011). "Genomic profiling of prostate cancer patients has identified a broad range of Wnt signaling components that are genetically altered (predominantly APC and CTNNB1) and highlighted Wnt pathway components as actionable therapeutic targets that may also harbor predictive value for metastatic disease." (PMID 35204808, 2022). "Indeed, a commercial test (ConfirmMDx for Prostate Cancer, MDx Health), based on APC (Adenomatous Polyposis Coli), GSTP1, and RASSF1 (Ras Association (RalGDS/AF-6) Domain Family Member 1) hypermethylation in cancer-negative biopsies, offers a negative predictive value of 90%39." (PMID 28084441, 2017). "For instance, 5% of prostate tumours harboured activating mutations in β-catenin, whereas changes in the coding region of Axin1 were recently identified in 6% of advanced prostate cancer and inactivating mutations in APC have not been found in prostate cancer patients." (PMID 19277043, 2009).
prostate carcinoma (continued). "In some cancer there are some epigenetic markers that has been discovered due to the fact that prostate cancers frequently contain methylation of the tumor suppressor genes GSTP1, RASSF1, and APC, these genes are regarded as cancer biomarkers." (PMID 39132504, 2024). "More recently, an assay that evaluates the methylation of GSTP1, SFRP2, IGFBP3, IGFBP7, APC and PTGS2 genes to specifically identify individuals with a severe probability of developing prostate cancer has been proposed." (PMID 37511475, 2023). "For example, the integrated analysis function of the prostate cancer organoids-on-a-chip can rapidly detect fluctuations in prostate cancer-related epigenetic biomarkers (RASSF1, APC, and RARb gene hypermethylation) before and after drug administration." (PMID 37304140, 2023). "It has been found that the promoter methylation levels of APC, TGFb2 and RASSF2001A in prostate cancer are related to Gleason score and pathological stage." (PMID 37190171, 2023). "For example, researchers can rapidly detect fluctuations in prostate cancer-related epigenetic biomarkers (RASSF1, APC, and RARb gene hypermethylation) before and after drug administration." (PMID 37304140, 2023). "We included primers for four genes in the pre-amplification pool (RASSF1, APC, RARB and GSTP1), which have previously been identified as being methylated in a large percentage of prostate cancers." (PMID 35272673, 2022). "Disulfiram’s anticancer activity is mediated by its ability to suppress DNMT1 and through the reactivation of epigenetically silenced genes such as APC and RARB in prostate cancer cell lines (Section 1)." (PMID 33312959, 2020). "Methylation biomarkers have been identified in prostate cancer previously, including promoter segments of GSTP1, RASSF1, and APC, which are used in commercial tissue-based test to identify patients needing repeat biopsies after an initial negative biopsy." (PMID 28412973, 2017). "Further, this can explain the difference between our results regarding the prognostic biomarker potential of APC and GSTP1 and a previous study where prostate cancer-specific death was also the primary endpoint." (PMID 25193387, 2014). "Some of the commonly reported hypermethylated genes in prostate cancer include GSTP1, RASSF1A, and APC, which have aided in prostate cancer diagnosis and prognosis." (PMID 24664224, 2014). "This study involved patients with high index of suspicion of prostate cancer; APC and GSTP1 methylation ratios below the threshold (predicting no cancer) produced an NPV of 96% and 80%, respectively, indicating that APC has significantly higher NPV." (PMID 27351008, 2014). "Aneuploidy, loss of heterozygosity, gene mutations, hypermethylation and inactivation of specific tumour suppressor genes such as GSTpi, APC, MDR1, GPX3 and others have been detected in prostate cancers, but generally only at a low or moderate frequency." (PMID 24282788, 2013). "APC and RASSF1 have also been described as prostate cancer markers with important roles in detecting the epigenetic field effect surrounding cancer foci." (PMID 22672250, 2012). "For example, GSTP1, RASSF1A, RAR2 and LGALS3 promoters are frequently methylated in prostate cancer; while ARF, APC, and DAPK have been found methylated in bladder cancer." (PMID 25419445, 2012). "Biomarkers like GSTP1, APC and RASSF1 have demonstrated involvement with prostate cancer, with the latter two genes playing prominent roles in the field effect." (PMID 22672250, 2012). "Although genetic and epigenetic changes activate Wnt/β-catenin signaling to drive the progression of prostate cancer, it is not commonly observed for CTNNB1, APC, and AXIN1 genes to undergo mutations in prostate cancer." (PMID 38886806, 2024).
prostate carcinoma (continued). "Besides, previous research has demonstrated that several transcription factors, such as FOXM1, MYC, APC/C/CDH1, and E2F, targeted RRM2 in prostate cancer." (PMID 36202136, 2022). "The APC tumor suppressor gene is involved for familial adenomatous polyposis (FAP) and initiates carcinogenesis for various cancer types such as colo-rectal cancer, prostate cancer, gastric cancer and breast cancer." (PMID 33369461, 2020). "Most notably, this has led to a commercially available test (ConfirmMDx for Prostate Cancer; MDx Health) with a reported negative predictive value of 90% in confirming negative biopsies based on qMSP analysis of APC, GSTP1, and RASSF139." (PMID 28084441, 2017). "Moreover, the annotated genes in the constructed network, such as APC, AXIN1, AKT2, CCND2, CAV1, TLE2 and TCF4, are essential regulatory components of these pathways in prostate cancer." (PMID 23782521, 2013). "Hypermethylation of multiple genes (including GSTP1, RAR-2β, and APC) identified prostate cancer in histopathologically negative biopsy samples collected from men who were later positively diagnosed during a follow-up biopsy procedure." (PMID 20671914, 2010). "Hypermethylation of the CCND2 promoter is significantly higher in prostate cancers compared to normal prostate tissues (32%, 6% resp.; P = 0.004), and there are statistically significant concordances between methylation of CCND2 and the methylation of RARβ, GSTP1, CDH13, RASSF1A, and APC genes." (PMID 22191037, 2011). "Multiple genes, such as GSTP1, APC, MDR1, MGMT, and RASSF1A, show higher methylation frequency in prostate cancer samples compared to BPH and non-neoplastic prostate samples." (PMID 37234978, 2023). "For example, hypermethylation in genes APC and GTSP1 was reported in 95% and 43% respectively in patients with an initial negative biopsy that later developed prostate cancer." (PMID 36131292, 2022). "An initial test cohort of 30 prostate cancer-positive samples and 12 cancer-negative samples was used as basis for the development and optimization of an epigenetic multiplex assay based on the GSTP1, APC and RASSF1 genes, using methylation specific PCR (MSP)." (PMID 22672250, 2012).
intestinal tumors (75 papers, 2009 to 2026). "In preclinical studies, the combination of APC and SMAD4 mutations resulted in a more malignant phenotype of intestinal tumors in mice compared with a single mutation of APC." (PMID 37190048, 2023). "Mice carrying adenomatous polyposis coli gene mutations, APC (Min/+), are susceptible to a variety of intestinal tumors." (PMID 32993749, 2020). "This mouse model carries heterozygous inactivating mutation of APC allele, which is associated to multiple intestinal neoplasms, a phenotype reminiscent of human FAP37." (PMID 33303756, 2020). "SGK1 expression also promotes the development of intestinal tumors in adenomatous polyposis coli (APC)-deficient mice, an effect at least partially due to enhanced beta-catenin protein abundance." (PMID 33542904, 2020). "For example, gene fusions involving R-spondin 1 occurring in 10% of intestinal tumor are mutually exclusive with active Wnt signaling caused by APC or CTNNB1 mutations." (PMID 31905853, 2019). "In APCmin/+ mice, a heterozygous germ line truncation in the APC gene results in the formation of intestinal tumors after spontaneous loss of heterozygosity of the remaining APC wt allele." (PMID 31694340, 2019). "We conclude that induction of an EMT program in primary tumor cells induces rapid metastatic dissemination in Drosophila intestinal tumors driven by APC and Ras mutations." (PMID 31127094, 2019). "In the model of intestinal cancer, we observed maintenance of the mutated APC gene in IEC monolayers derived from intestinal tumors of ApcMin/+ animals." (PMID 30111276, 2018). "Mouse models combining mutations of APC with the expression of an oncogenic KRASG12V/+ induced an increased number of intestinal tumors, endowed with increased tissue invasiveness." (PMID 29652830, 2018). "In fact, the targeted deletion of JAGGED1 in LGR5+ tumor-initiating cells resulted in the silencing of HES1 expression, the disruption of the stem cell niche and a dramatic reduction in the proliferative activity of APC-deficient intestinal tumors in vivo." (PMID 29652830, 2018). "Human intestinal tumors frequently occur in a setting of adenomatous polyposis coli (APC) loss, active Wnt signaling and KRAS activation." (PMID 30171151, 2018). "In mice, presence of a KRAS mutation in an APC mutant background was also associated with reduced survival due to accelerated growth of intestinal tumors." (PMID 27729614, 2016). "All the alleles that cause a loss of the ability of APC to bind β‐catenin lead to intestinal tumour predisposition; however, precise kinetics and tumour features can alter depending on the allele." (PMID 26414675, 2016). "APC-driven intestinal tumor formation in humans is associated with bi-allelic mutations or loss of the wild type copy evidenced by loss of heterozygosity." (PMID 26097888, 2015). "The various APC truncation mutations identified suggest molecular complexity of the mechanism(s) by which deregulated Wnt/β-catenin signaling drives intestinal tumor formation." (PMID 26398937, 2015). "Moreover, APC mutations have been reported to induce intestinal tumors by activating the Wnt signaling pathway in epithelial cells." (PMID 40690457, 2025). "Intestinal tumors can spontaneously form in APC-related mouse models, which have been designed to contain germline mutations in the APC gene that result in expression of a truncated APC protein." (PMID 36831495, 2023). "Additionally, we examined the ApcMin mouse model of APC/β-catenin-dependent intestinal tumors for susceptibility of such effects of MACC1 in vivo by means of IHC and RT-qPCR." (PMID 36008464, 2022).